ENSG00000238570
Synonyms: LOC124906148
Gene: Small nucleolar RNA gene on chromosome 2 (161,558,544 to 161,558,646, forward strand). Ensembl gene ENSG00000238570.
Gene Ontology:
Biological process: RNA processing
Cellular component: nucleolus
Homologues: Paralogues in human: SNORD13D (89% identical), SNORD13P1 (87% identical), SNORD13 (86% identical), SNORD13E (85% identical), SNORD13P3 (83% identical).